PHOX2B (paired like homeobox 2B)
Diseases named in the same sentence as PHOX2B in open-access papers (continued):
Sharing a sentence is not in itself a finding about the gene and the disease.
neuroblastoma (continued). "Genetic defects in PHOX2B have been described primarily with congenital central hypoventilation syndrome (CCHS), which occur with HSCR in 15–20% of cases and in some reports with neuroblastoma." (PMID 34422713, 2021). "Significant expression of (nor-)adrenergic (“NOR”) markers (i.e., CHGA, CHGB, DBH, TH, PHOX2A, and PHOX2B) is common for healthy sympatho-adrenal cells and tumor NOR populations identified in low-risk neuroblastoma cases (FDR < 0.01, Welch’s t-test)." (PMID 34493726, 2021). "In terms of rare coding variants, a de novo in-frame deletion in PHOX2B in a female patient with L-HSCR and other anomalies but without clinical manifestations of CCHS or neuroblastoma has been described." (PMID 34422713, 2021). "We identified 88 transcription factors, many of which have been described previously as part of the core regulatory transcription factor circuitry in specific cancer types, such as PHOX2B, TWIST1, and ISL1 in neuroblastoma; MYOD1 and MYOG in rhabdomyosarcoma; NR0B1 in Ewing sarcoma." (PMID 34818552, 2021). "In contrast, a PDX model established for patient A7012 from cytogenetic residual cells (CCI-NB03-DPC) showed features of poorly differentiated neuroblastoma consistent with the original tumour, NB84 and PHOX2B positivity, and strongly correlated with the patient material by SNP array (r = 0.71)." (PMID 31919402, 2020). "This xenograft was positive for the B-lineage marker CD20 and negative for the neuroblastoma markers PHOX2B and NB84, and negative for the T-cell marker CD3." (PMID 31919402, 2020). "In neuroblastoma, stable PBX1-MEIS1 interaction provides an overexpression of Phox2b." (PMID 33402862, 2020). "In addition, LMO1 occupancy was associated with enrichment of transcription factors that have previously been shown as members of the ADRN neuroblastoma CRC, including PHOX2B, HAND2, TBX2, and ISL15,19–21 (left)." (PMID 31819055, 2019). "These new genetic findings indicate the potential pleiotropic effects of PHOX2B in both HSCR and neuroblastoma, which could guide the development of therapeutic targets for the treatment of related neurodevelopmental disorders." (PMID 30799307, 2019). "Taken together, our data on PHOX2B gene expression and neuroblastoma cell proliferation and apoptosis showed that MMF and CQ are the most effective drugs among those selected through HTS in counteracting neuroblastoma." (PMID 29069774, 2017). "PHOX2B and its paralogue gene PHOX2A are two homeodomain proteins in the network regulating the development of autonomic ganglia that have been associated with the pathogenesis of neuroblastoma (NB), because of their over-expression in different NB cell lines and tumour samples." (PMID 26902400, 2016). "Tumorigenesis and metastasis of neuroblastoma cells in vivo are regulated by a balanced function of positive and negative signals including those regulated by PHOX2B." (PMID 26840262, 2016). "PHOX2B has not yet been targeted for development of therapeutics given the low frequency of involvement in neuroblastoma." (PMID 26771642, 2016). "In some cases PHOX2B point mutations/deletions have been reported in patients without CCHS and presenting neuroblastoma (NB, OMIM 256700), HSCR or both." (PMID 23342068, 2013). "Neuroblastoma development in TH-MYCN transgenic mice begins with hyperplastic lesions in early postnatal sympathetic ganglia that are composed predominantly of Phox2b-positive but Th-negative neuronal progenitors." (PMID 23754957, 2013). "Here, neuroblastoma (NB) cell line subtypes were characterized according to embryonic peripheral nervous system development markers (GAP43, Phox2b, Sox10, c-kit, GD2, NF68, vimentin, S100β, calcyclin and ABCG2), morphological features, gene expression and differentiation potential." (PMID 19216736, 2009).
neuroblastoma (continued). "Neuroblastoma derives from embryonic neural crest cells, and in NB tumors that harbor amplification of the proto-oncogene MYCN, a transcriptional core regulatory circuitry (CRC) that includes MYCN, HAND2, ISL1, PHOX2B, GATA3, and TBX2 promotes tumorigenesis." (PMID 40766465, 2025). "This variant was found to be located in open chromatin regions identified in 29 ATAC‐seq and 5 H3K27ac ChIP‐seq experiments in various neuroblastoma cell lines, but also showed the highest enrichment of TF binding sites, including MYCN, LMO1, GATA3, HAND2, ISL1, PHOX2B, and TBX2." (PMID 40525640, 2025). "Indeed, a heterogenic pool of mutations in the PHOX2B gene have been observed in familial and sporadic forms of neuroblastoma, but in most neuroblastoma cells PHOX2B is highly expressed rather than downregulated." (PMID 38666930, 2024). "Indeed, MYCN, ISL1, HAND2, and PHOX2B, together with GATA3 and TBX2, comprise the core regulatory circuit, an autoregulatory transcriptional loop that maintains the malignant phenotype of MYCN-positive neuroblastoma." (PMID 37297004, 2023). "However, as many as 50% of adult neuroblastomas, including the current tumor, do not express PHOX2B, implying a potential divergence in the cell lineage from which these tumors originate." (PMID 38031161, 2023). "In 2017, the International Neuroblastoma Response Criteria Bone Marrow Working Group recommended the collection of both bilateral BM biopsies and aspirates and their analysis with immunohistochemistry for GD2 and RTqPCR for tyrosine hydroxylase and paired-like homeobox 2B (PHOX2B)." (PMID 34623519, 2022). "These authors found that the neuroblastoma immunopeptidome is enriched with peptides derived from proteins that are essential for tumorigenesis and focused on targeting the unmutated peptide QYNPIRTTF, discovered on HLA-A*24:02, derived from the neuroblastoma master transcriptional regulator PHOX2B." (PMID 35795050, 2022). "Moreover, by whole exome sequencing, we demonstrated that NB exo-DNA represents the entire exome and that it carries tumor-specific genetic mutations, including those occurring on known oncogenes and tumor suppressor genes in neuroblastoma (ALK, CHD5, SHANK2, PHOX2B, TERT, FGFR1, and BRAF)." (PMID 33915956, 2021). "However, PHOX2B was not highly expressed in all neuroblastoma tumors and its expression considerably varied among different neuroblastoma patients." (PMID 31214500, 2019). "Finally, not all supposed NB‐specific markers are expressed by all DTCs, as we could, for example, show for PHOX2B, the widely used MRD marker in neuroblastoma." (PMID 28921546, 2018). "Indeed, an example is the screening of compounds against the neuroblastoma cell line IMR32, from which it was discovered that the PHOX2B gene might be targetable by influencing its direct transcriptional regulators, such as Meis-1, NF-κB and AP-1." (PMID 28178969, 2017). "TBX2 (T-box 2 transcription factor) is a constituent of the NOR CRC in neuroblastoma cells, together with HAND2, GATA3, and PHOX2B." (PMID 34200747, 2021). "Stage 2B neuroblastoma was more heterogeneous in DBH and PHOX2B expression, with all cells lacking expression of PRRX1 and very few cells positive for PDGFRA." (PMID 34493726, 2021). "Since MES cells do not express the typical markers (PHOX2B, TH, or DBH) used in clinical routine to characterize neuroblastoma cells, their detection requires the use of other markers or technics." (PMID 34200747, 2021). "Blastemal type WTs and neuroblastomas are both positive for CD56, but WT1 is negative in neuroblastoma, while synaptophysin, chromogranin A, NB84, and PHOX2B are positive in neuroblastoma." (PMID 32204536, 2020). "SK-N-SH neuroblastoma cell was shown to express RET, NKX2-1, PHOX2B, but not SOX10, PAX3." (PMID 21677782, 2011).
neuroblastoma (continued). "However, since PHOX2B and TH were markers of the adrenergic (ADR) super-enhancer state, and were not universally expressed by neuroblastoma cells, a further understanding of the gene expression landscape of these neuroblastoma CTCs, including markers of the mesenchymal (MES) state, was required." (PMID 36176417, 2022).
congenital central hypoventilation syndrome (28 papers, 2013 to 2026). "Pathogenic heterozygous variants in PHOX2B are associated with congenital central hypoventilation syndrome (CCHS), which is characterized by autonomic nervous system dysregulation severely affecting respiratory control." (PMID 41809564, 2026). "Heterozygous mutations in the PHOX2B gene are associated with neurodevelopmental disorders, including congenital central hypoventilation syndrome and Hirschsprung's disease." (PMID 41578938, 2026). "Congenital central hypoventilation syndrome (CCHS) is a rare genetic disease associated with mutations of the PHOX2B gene and characterized by life-threatening breathing deficiencies." (PMID 40387080, 2025). "The paired-like homeobox 2B (PHOX2B) gene is also involved in neural crest development, and loss of function mutations result in Central Congenital Hypoventilation Syndrome (CCHS)." (PMID 37239446, 2023). "Congenital central hypoventilation syndrome (CCHS) is a rare autosomal-dominant disorder of the autonomic nervous system that results from mutations in the PHOX2B gene." (PMID 37373665, 2023). "Congenital central hypoventilation syndrome (CCHS) is a rare disorder of the autonomic nervous system (ANS) that results from mutations in the paired-like homeobox 2b (PHOX2B) gene located on chromosome 4p12." (PMID 37373665, 2023). "Congenital central hypoventilation syndrome (CCHS) is a rare genetic disorder caused by mutations in the Paired-Like Homeobox 2B (PHOX2B) gene." (PMID 35209861, 2022). "Mutations in the PHOX2B gene cause congenital central hypoventilation syndrome (CCHS), a rare autonomic nervous system dysfunction disorder characterized by a decreased ventilatory response to hypercapnia." (PMID 33047879, 2020). "Congenital central hypoventilation syndrome (CCHS) is a rare neuro-respiratory disorder associated with mutations of the PHOX2B gene." (PMID 24475031, 2014). "Congenital central hypoventilation syndrome (CCHS) is a rare neuro-respiratory disorder associated with several possible mutations of the PHOX2B gene." (PMID 24475031, 2014). "PHOX2B is the major disease causing gene in Congenital Central Hypoventilation Syndrome (CCHS, OMIM 209880), that is associated with sympathetic tumour and Hirschsprung disease (HSCR, OMIM 142623) in 5 and 20% of cases respectively." (PMID 23342068, 2013). "Congenital central hypoventilation syndrome (CCHS) is a rare disorder of autonomic control of breathing caused predominantly by paired-like homeobox 2B (PHOX2B) mutations and frequently accompanied by broader autonomic dysfunction affecting cardiovascular, gastrointestinal, and endocrine systems." (PMID 41531556, 2025). "Our previous findings showed that stimulation of NTSPhox2b neurons potentiate ventilation, presenting a plausible central intervention point for SDB conditions like congenital central hypoventilation syndrome, which is characterized by mutations in Phox2b within affected individuals." (PMID 38553555, 2024). "PHOX2B is required for Ret expression in mouse pre-ENCDCs, and heterozygous PHOX2B polyalanine-expansion mutations cause congenital central hypoventilation syndrome (i.e., central sleep apnea) in humans, a syndrome that may include HSCR (Haddad syndrome)." (PMID 23639815, 2013). "Congenital central hypoventilation syndrome (CCHS), which is caused by PHOX2B with phenotypic variations, has a point of controversy: CCHS is putatively involved in autopsy cases of sudden unexpected infant death (SUID) including sudden infant death syndrome." (PMID 35486589, 2022). "Congenital central hypoventilation syndrome (CCHS) is a rare disease characterized by central alveolar hypoventilation and impaired autonomic regulation, caused by pathogenic variants of PHOX2B gene." (PMID 36874254, 2022). "Congenital central hypoventilation syndrome (CCHS) is a genetic disorder of neurodevelopment, with an autosomal dominant transmission, caused by heterozygous mutations in the PHOX2B gene." (PMID 33510615, 2020).
congenital central hypoventilation syndrome (continued). "Mutation of the paired-like homeobox 2B gene (PHOX2B) is a defining factor in patients with congenital central hypoventilation syndrome (CCHS), but not in those with ROHHAD." (PMID 37456561, 2023). "The final missed diagnosis had a polyalanine repeat expansion in the PHOX2B gene, a well-described variant causing congenital central hypoventilation syndrome, missed due to lack of read coverage in the responsible low-complexity gene region." (PMID 37291213, 2023). "Congenital central hypoventilation syndrome (CCHS) is a rare complex condition, characterized by impaired chemosensitivity and autonomic disfunction, which is caused by the genetic mutation of the transcription factor paired-like homeobox 2b (PHOX2B)." (PMID 35563209, 2022). "Congenital central hypoventilation syndrome (CCHS), previously known as Ondine’s curse, is an autosomal dominant disorder that results from a heterozygous mutation in the paired-like homeobox 2B gene (PHOX2B) on chromosome 4p13 in the majority of patients (OMIM #209880, #603851)." (PMID 28895939, 2017).
Hirschsprung disease (23 papers, 2010 to 2026). Hirschsprung disease (HSCR) is a congenital intestinal motility disorder that is characterized by signs of intestinal obstruction due to the presence of an aganglionic segment of variable extent in the terminal part of the colon. "NOA patient (case 31) with PHOX2B p.Phe33fs variant had been diagnosed with Hirschsprung disease and ileus, neoplasms of unclear nature, and unilateral cryptorchidism." (PMID 40060932, 2025). "CCHS patients with PHOX2B mutations frequently manifest Hirschsprung’s disease, revealing that genetic disturbances on PHOX2B can simultaneously alter the development of both the central and peripheral nervous systems." (PMID 36523603, 2022). "Linkage studies firstly identified missense or frameshift mutations in the paired-like homeobox 2B (PHOX2B) gene in a small group of familial NBs associated with Hirschsprung disease, congenital hypoventilation syndrome, and neurofibromatosis." (PMID 34072462, 2021). "Previous investigations have shown that the PHOX2B rs28647582 T>C polymorphism significantly alters Hirschsprung disease susceptibility." (PMID 31652452, 2019). "Further studies in additional series of patients are necessary to deepen in our knowledge of the association between Hirschsprung disease and PHOX2B gene." (PMID 23342068, 2013). "In addition to CCHS PHOX2B variants define a broad phenotypic spectrum, including Hirschsprung disease, apparent life-threatening event (ALTE) and sudden infant death syndrome (SIDS)." (PMID 34757495, 2021). "PHOX2B mutations are observed in rare hereditary forms of NB and Hirschsprung’s disease." (PMID 23106811, 2012). "Although it could not be confirmed by histological examination, it is highly plausible that her gastrointestinal symptoms are attributable to mild Hirschsprung disease given the presence of anisocoria, respiratory insufficiency, and a pathogenic PHOX2B variant." (PMID 33047879, 2020). "Moreover, this co-culture system could be used to mechanistically study of Hirschsprung's disease, caused by a mutation in the PHOX2B gene in human." (PMID 32509598, 2020). "Complete deletion of the PHOX2B gene is a rare event which has been observed in a patient with Hirschsprung's disease and in three families with CCHS." (PMID 25928806, 2014). "PHOX2B mutations are often found in association with other neurocristopathies such as Congenital Central Hypoventilation Syndrome (CCHS) and Hirschsprung disease (HSCR), likely modifying susceptibility to NB in the corresponding patients." (PMID 20957039, 2010).
Arrhythmia (3 papers, 2013 to 2021). Any cardiac rhythm other than the normal sinus rhythm. "Mutation of PHOX2B in humans causes congenital central hypoventilation syndrome, which has cardiac arrhythmia as one of its incompletely penetrant symptoms." (PMID 34488850, 2021). "PHOX2B mutation carriers are at risk for chronic hypoventilation and arrhythmias and must be assessed and managed by specialists familiar with CCHS." (PMID 23622117, 2013). "CCHS patients are at a higher risk of autonomic heart rhythm dysfunction or arrhythmias, which might be associated with PHOX2B gene mutations and following hypothalamic functional abnormalities." (PMID 34949014, 2021). "Cardiac arrhythmias are common in CCHS; even though there are differences in their prevalence depending on the PHOX2B mutation type, researchers recommend screening to be a standard procedure in all patients." (PMID 34949014, 2021).
metastatic disease (3 papers, 2017 to 2023). "The metastatic tumor harbored a PHOX2B deletion and a missense mutation of NRAS (p.Gln61Lys), whereas an ALK mutation (p.Phe1174Leu) was detected only in the primary tumor." (PMID 28915622, 2017). "In contrast, in 14/30 samples of patients with metastatic disease, PHOX2B (n = 13, 9.2 copies/mL, range 0.4–47 copies/mL) and/or CHRNA3 (n = 4, mean 5.4 copies/mL, range 2.1–11 copies/mL) was detected." (PMID 37046768, 2023).
osteosarcoma (3 papers, 2014 to 2025). A usually aggressive malignant bone-forming mesenchymal neoplasm, predominantly affecting adolescents and young adults. "In contrast, MONC-1 cells gave rise to various tumor types, as 3/7 mice developed osteosarcoma with chondrosarcoma components, 1/7 mouse developed a highly malignant Phox2b−/nestin+ undifferentiated tumor, and 3/7 mice developed Phox2b+/Th−/nestin− undifferentiated NB." (PMID 24947326, 2014).
ROHHAD syndrome (3 papers, 2018 to 2024). "Since patients with ROHHAD syndrome resemble congenital hypoventilation syndrome patients, PHOX2B, a gene encoding a transcription factor critical for hypothalamic embryogenesis, was investigated but no abnormalities were found." (PMID 29553042, 2018). "The PHOX2B variant is the point for differentiation between ROHHAD syndrome and CCHS." (PMID 35805903, 2022).
schizophrenia (3 papers, 2017 to 2024). A major psychotic disorder characterized by abnormalities in the perception or expression of reality. "The schizophrenia- and strabismus-implicated PHOX2B gene was expressed at a lower level in medial rectus muscles than lateral rectus muscles, but the reduction (to 54%) was not statistically significant in our data set (p = 0.14, n = 5)." (PMID 29302405, 2017). "So far, only a few risk genes were shown to be shared between strabismus and schizophrenia: PMX2B or PHOX2B/ARIX, and AHI1, although additional ones may exist." (PMID 29302405, 2017). "Although expression of PHOX2B (PMX2B/ARIX), which has been implicated in both strabismus and schizophrenia, was reduced to 50% in the muscles from patients with strabismus, this reduction was not statistically significant in our data set (p = 0.13, n = 4)." (PMID 29302405, 2017).
Apnea (2 papers, 2020 to 2023). Lack of breathing with no movement of the respiratory muscles and no exchange of air in the lungs.